VIM (vimentin)
Diseases named in the same sentence as VIM in open-access papers (continued):
Sharing a sentence is not in itself a finding about the gene and the disease.
melanoma (235 papers, 2007 to 2026). A malignant, usually aggressive tumor composed of atypical, neoplastic melanocytes. "In melanoma, elevated levels of vimentin, a mesenchymal EMT marker, are associated with the high invasive and migratory potential of cancer cells and with a poor clinical outcome." (PMID 38247872, 2024). "Downregulation of both vimentin and nestin has been previously linked to drug resistance in melanoma, as well as upregulation of processes such as PI3K/AKT signaling, remodeling of focal adhesions, actin cytoskeleton, and integrin signaling." (PMID 39086667, 2023). "Instead, in male melanoma cell lines, where an unchanged level of ERβ in acidosis is associated with an enhanced expression of N-cadherin and vimentin, cell invasiveness increases." (PMID 36499700, 2022). "Vimentin is proved to be not only the diagnostic marker but also the hematogenous metastasis predictor for melanomas clinically." (PMID 36338621, 2022). "This phenomenon, that resembles the Epithelial-Mesenchymal Transition (EMT), involves the decrease of E-cadherin, the increase of mesenchymal proteins (N-cadherin, vimentin) and causes a migratory and invasive phenotype in melanomas." (PMID 36400750, 2022). "Surprisingly, the expression of HopQ in melanoma cells caused a previously undescribed intracellular response, i.e., a specific decrease in vimentin protein, apparently unrelated to known mechanisms of 14-3-3-induced metastasis." (PMID 32286254, 2020). "Using microarrays data we show that both SNAI1 (gene encoding SNAI/Snail) and VIM (gene encoding vimentin) expression levels exhibited positive correlation with TMSB4X expression in human melanoma patients." (PMID 31921836, 2019). "Overexpression of HMB45, vimentin, and S100 is known to be strongly associated with malignant melanoma, although variations in the immunohistochemical expression pattern are common." (PMID 28865487, 2017). "In the present study, analysis of sorafenib treated BRAF-mutated melanoma cells and xenograft tumor tissues showed reduced protein expression of mesenchymal marker proteins (N-cadherin, vimentin and fibronectin)." (PMID 26517521, 2016). "Recent studies have revealed that vimentin is not only a diagnostic marker but also a hematogenous metastasis clinical predictor for melanoma." (PMID 24392146, 2014). "The data showed that high expression of vimentin was significantly associated with melanoma hematogenous metastasis." (PMID 20701774, 2010). "It has been reported by the University of Iowa Health Care research group and by others that the co-expression of vimentin along with keratins in human melanoma is associated with recurrent and metastatic disease." (PMID 18847500, 2008). "Recent reports have reported the expression of vimentin in numerous neoplasms, including melanoma, which has been linked to metastatic disease." (PMID 18847500, 2008). "In a previous study aimed at identifying biomarkers associated with pulmonary metastasis of melanoma, high vimentin expression was associated with melanoma-derived lung metastasis, and the overexpression of vimentin was frequently observed in primary melanoma patients with hematogenous metastasis." (PMID 32286254, 2020). "In this sense, vimentin might act as a clinical predictor for melanoma, to provide means to predict high-risk patients for haematogenous metastasis, and thus to provide individualised treatment options." (PMID 30248895, 2018). "Melanomas break free from the homeostatic control of keratinocytes by loss in expression of E-cadherin, upregulation of expression of fibroblast interacting cadherins like N-cadherin, and upregulation of mesenchymal markers like vimentin." (PMID 28223541, 2017). "Furthermore, vimentin histology demonstrated the presence of mesenchymal cells both within and around the evolved tumor masses, strongly associating with the microenvironment characteristics of human melanoma." (PMID 41255880, 2025).
melanoma (continued). "Furthermore, treatment of fisetin promoted mesenchymal to epithelial transition in melanoma cells, which was associated with a decrease in mesenchymal markers (N-cadherin, vimentin, snail and fibronectin) and an increase in epithelial markers (E-cadherin and desmoglein)." (PMID 24466036, 2014). "In agreement with the differential abundance analysis, APCA+ on the cell type indicates that monocytes are characterized by high intensities of CORO1A, LCP1, TMSB4X, and RPL13, while melanoma cells are characterized by higher intensities of VIM and MCALL1." (PMID 40775377, 2025). "This demonstrates the mesenchymal character of all cell lines, in agreement with the ubiquitously high expression of the mesenchymal marker Vimentin in melanoma." (PMID 40754577, 2025). "When comparing monocytes to melanoma cells, proteins such as VIM, LMNA, CALU, LGALS3, CTTN, and CORO1A are strongly and confidently differentially expressed." (PMID 40775377, 2025). "Our findings corroborate with previous reports demonstrating ZEB1-mediated regulation of N-cadherin in prostate cancer cells and vimentin in melanoma." (PMID 40664642, 2025). "Sarcoma histological markers are sometimes common with melanomas detection (for example, S100 protein, vimentin, exceptionally HMB-45 and Melan-A)." (PMID 39862670, 2025). "SRPK inhibitors potentially suppressed melanoma cell survivability and metastasis through the triggering of apoptotic proteins and dysregulating vimentin." (PMID 41403742, 2025). "In the first step, lineage‐specific markers (CK, S100, LCA, and Vimentin) are screened to distinguish carcinoma from lymphoma, sarcoma, and melanoma." (PMID 40242159, 2025). "Tumor cells in melanoma show positivity for S-100, HMB-45, vimentin, Melan-A, tyrosinase, and microphthalmia-associated transcription factor (MITF)." (PMID 39280438, 2024). "Exogenous Wnt5a interventions, for instance, increase the expression of vimentin, snail, and other interstitial markers of melanoma cells, which promotes melanoma metastasis." (PMID 38898476, 2024). "In our patient, an accurate diagnosis was made due to the presence of IHC markers such as HMB-45, MELAN-A, and S-100, which indicate melanoma; synaptophysin and vimentin, which indicate neuroendocrine origin; and pan-CK and CK20, which ruled out carcinoma." (PMID 39624501, 2024). "Positive expression of protein S-100, melanoma antigen HMB-45, and vimentin is commonly observed in malignant melanoma." (PMID 39624501, 2024). "p3 anoikis-resistant melanoma cells showed a higher level of the EMT markers N-Cadherin, Vimentin, Zeb1, and SNAIL1, associated with high invasive ability and low IKB expression, which indicates NF-kB activation." (PMID 39175551, 2024). "Treatment of melanoma cell lines with PEBP and OMP resulted in the overexpression of miR-200c, which caused the negative regulation of ZEB2 and vimentin and up-regulated E-cadherin." (PMID 38255297, 2024). "An adipocyte CM-induced invasion of B16BL6 melanoma cells was associated with an increased expression of EMT genes such as snail, twist, and vimentin mRNA levels." (PMID 38999849, 2024). "The transfection of miR-200c inhibitor resulted in increased ZEB2 and Vimentin and decreased expression of E-cadherin in the melanoma cancer stem cells from the control group." (PMID 38255297, 2024). "Western blotting assay revealed elevated levels of the epithelial marker E‐cadherin protein and reduced levels of the mesenchymal markers vimentin and SNAL1 protein in USP22‐deficient melanoma cells." (PMID 39135915, 2024). "Previous studies demonstrated that nestin knock-out does not affect vimentin expression, which suggests that YB-1 plays some role in the upregulation of both nestin and vimentin, which are both highly relevant prognostic markers of malignancy in melanoma." (PMID 39086667, 2023).
melanoma (continued). "As evidenced by a decrease in mesenchymal markers (N-cadherin, vimentin, snail, and fibronectin) and an increase in epithelial indicators, fisetin also accelerated the phenotypic shift of melanomas from mesenchymal to epithelial (E-cadherin and desmoglein)." (PMID 37565061, 2023). "In this study, loss of LINC00511 also upregulated E-cadherin expression, downregulated Vimentin, snail, and N-cadherin to suppress epithelial–mesenchymal transition of melanoma." (PMID 36874361, 2023). "High levels of ZEB1/Slug and Oct4 expression, as we showed here, certainly sustain an invasive phenotype in melanoma, including increased expression of vimentin." (PMID 37189846, 2023). "EMT-related markers include N-cadherin, E-cadherin, vimentin, and Snail, which have been documented in lots of cancers, such as breast, colorectal, oral, lung, pancreatic, melanoma, and liver cancers." (PMID 36866240, 2023). "To characterize PAX6-negative cells, we performed double immunostaining on corneoscleral tissue sections using epithelial (keratin marker, Pan-CK), stromal (vimentin), and melanocytic (Melan-A and human melanoma black−45 (HMB−45)) markers." (PMID 36766742, 2023). "Adipocytes cocultured with melanoma presented fibroblastic features, such as a similar proteolytic pattern to that of 3T3L1 fibroblasts and increased levels of vimentin and TGFβRIII." (PMID 37481560, 2023). "Immunostaining revealed the presence of PAX6-negative cells which were positive for vimentin and the melanocyte markers Melan-A and human melanoma black-45 in the basal layer of the limbal epithelium." (PMID 36766742, 2023). "It reduces the migratory ability of melanoma cells through the regulation of E‐cadherin/vimentin and MMP‐2/MMP‐9 expression." (PMID 37038620, 2023). "Later, Patel and Sharma (2016) reported that quercetin in SK-MEL-28 human melanoma reversed collagen I-induced EMT via suppression of the expression of mesenchymal markers including vimentin, N-cadherin, Twist, and SNAIL." (PMID 37687080, 2023). "In fact, the iβ4− cell population showed significant upregulation of the following proteins: CSC1-like protein 2 and Vimentin (both expressed in Langerhans cells) and melanoma antigen (expressed in melanocytes)." (PMID 35883599, 2022). "We evaluated by real-time PCR the expression level of N-cadherin and vimentin both in female and male melanoma cells and we found that in double silenced cells the expression of these EMT markers was as low as the level obtained after NF-ΚB silencing." (PMID 36499700, 2022). "Increased vimentin expression has been reportedin various epithelial cancers (prostate, breast, melanoma, lung, gastrointestinal,and CNS tumors), correlating with increased tumor growth, invasion, and poorprognosis." (PMID 35107490, 2022). "In a mouse model of subcutaneously grafted B16F10 melanoma, anti-vimentin antibodies inhibited tumor growth and tumor vessel density." (PMID 35606362, 2022). "In parallel experiments, the silencing of NF-κB drives a rapid increase of ERβ and a decrease of EMT markers, N-cadherin, vimentin, Zeb1, both in female and male melanoma cells." (PMID 36499700, 2022). "Immuno-staining for Human Melanoma Black-45, Soluble 100% and vimentin are of invaluable help to make an accurate diagnosis." (PMID 35382743, 2022). "Melanoma cultures were also stained for fibroblast (vimentin), melanoma (tyrosinase), and dendridic cell (CD11c) markers at day 0 and day 14 by immunohistochemistry." (PMID 35162988, 2022). "We excluded the possibility of metastatic clear renal cell carcinoma, neuroendocrine carcinoma, perivascular epithelioid cell tumor, malignant melanoma, and sarcoma because of the negativity for vimentin, chromogranin, synaptophysin, and HMB45." (PMID 36140448, 2022). "Our previous reports confirmed that Smad2/3 and Par6/aPKC/RhoA pathways upregulate the expression of Vimentin along with aPKCs in melanoma cells." (PMID 33525953, 2021).
melanoma (continued). "After lowering the Tβ4 level in melanoma cells, we observed an increased number of F-actin structures, along with Nestin and Vimentin’s location around the cell nucleus." (PMID 33807338, 2021). "In summary, the actin cytoskeleton, Nestin, and Vimentin filaments were organized significantly differently in melanoma cells with low Tβ4 levels than the cells with high TMSB4X expression." (PMID 33807338, 2021). "Culture medium from antigen-stimulated lung mast cells increased expression levels of HDAC3, MCP1, SNAIL, and Vimentin but decreased the expression of E-cadherin in B16F1 melanoma cells." (PMID 34135893, 2021). "We found that vimentin levels were significantly reduced in HopQ-expressing human melanoma cell lines." (PMID 32286254, 2020). "To further validate that ectopic expression of HopQ induces autophagy in melanoma cells, leading to suppressed vimentin expression, we disrupted autophagy by silencing ATG5 and ATG7 with siRNA." (PMID 32286254, 2020). "As the NH domain is essential for the binding of HopQ to vimentin, ubiquitination, and binding to p62, it is conceivable that the NH domain alone would exert an inhibitory effect on melanoma metastasis." (PMID 32286254, 2020). "As expected, mRNA transcripts for intermediate filament vimentin (VIM) were strongly transcribed in both cell types, i.e., in fibroblasts and melanoma cells and also in clinical samples." (PMID 33182777, 2020). "In melanoma cells, it binds Vimentin (VIM) and RAC1 mRNAs to increase their translation and trigger metastasis." (PMID 32161113, 2020). "In this study, we demonstrated that the HopQ from a plant pathogen Pto also interacts with 14-3-3 in melanoma cells and regulates vimentin stability, thus inhibiting metastasis of melanoma cells." (PMID 32286254, 2020). "Further study showed that shikonin decreased the levels of STAT3-targeted genes Mcl-1, Bcl-2, MMP-2, vimentin, and Twist, which are involved in melanoma survival, migration, and invasion." (PMID 32536866, 2020). "In melanoma, UNR is usually highly expressed in melanoma and associated with invasion and metastasis by activating the extension of VIM and RAC1 mRNA." (PMID 32653017, 2020). "In conclusion, our study demonstrated that the effector protein HopQ from a plant pathogenic bacterium Pto interacts with a human protein 14-3-3 in melanoma cells and decreasing vimentin stability, thus inhibiting metastasis of melanoma cells." (PMID 32286254, 2020). "The level of epithelial cell marker (E-cadherin) was increased, whereas the levels of the mesenchymal markers (N-cadherin and vimentin) were decreased in LINC00520 knockdown melanoma cells." (PMID 32466797, 2020). "In melanoma cells, overexpressed HopQ is phosphorylated and bound to 14-3-3 through its N-terminal domain, resulting in stronger interaction between HopQ and vimentin." (PMID 32286254, 2020). "E-cadherin expression increased in the melanoma cells, while the expression of N-cadherin and vimentin decreased after the knockdown of FGFR3 in A357 cells." (PMID 31619201, 2019). "It has been previously reported how UNR/CSDE1 regulates direct translation of vimentin in melanoma cells." (PMID 31027221, 2019). "Analysis of vimentin mRNA transcript levels in the TCGA database shows that it is present in all types of malignancies, where most invasive cancer types like melanoma and glioma show the highest levels." (PMID 30987208, 2019). "The anti-metastasis effects of fisetin (5–20 μM) were revealed in melanoma cells, occurring through downregulation of mesenchymal markers (vimentin, N-cadherin, snail, and fibronectin) and upregulation of epithelial markers (desmoglein and E-cadherin)." (PMID 31064104, 2019). "Many studies have identified vimentin as a key component of cell invasion and metastasis in malignant melanoma." (PMID 30248895, 2018). "We examined EMT markers in fisetin-treated A375 melanoma cells and observed a decrease in vimentin and N-cadherin accompanied by an increase in E-cadherin." (PMID 30356079, 2018).
melanoma (continued). "MUG-Mel2 cells also highly express vimentin, a cytoskeletal protein, which is present in several melanoma cells." (PMID 28522871, 2017). "The combined inhibition of PKCζ and COX-2 induced Mesenchymal-Epithelial Transition (MET) in melanoma cells with the expression of E-Cadherin increasing and Vimentin decreasing." (PMID 28865485, 2017). "Silencing ROR1 expression in melanoma significantly inhibits cell migration and invasion through decreasing expression of vimentin and N-cadherin." (PMID 28427197, 2017). "In these cells, CSDE1 induces VIM protein expression with pro-oncogenic effects that contribute to melanoma invasion and metastasis." (PMID 29129916, 2017). "Knocking down of Zeb2 leads to significant downregulation of MITF and concomitant upregulation of Zeb1, Vimentin and Fibronectin resulted in enhanced melanoma progression." (PMID 28137308, 2017). "In agreement with its fibroblastic phenotypes, Rn, Bk and Rk melanoma cell lines, were positive for the mesenchymal marker vimentin." (PMID 29344558, 2017). "We discovered that tumor cells had decreased E‐cadherin expression and increased N‐cadherin and Vimentin expression in melanoma tumors formed from B16F10; bcat/Fb mixture." (PMID 27061029, 2016). "High levels of ZEB1 expression undoubtedly promote an invasive phenotype in melanoma, including decreased E‐cadherin and increased expression of Vimentin, SPARC, and MMPs." (PMID 27596438, 2016). "Associations between UBE3C and the epithelial-mesenchymal transition (EMT) markers E-cadherin and vimentin were also assessed in both melanoma tissues and cell lines." (PMID 26894856, 2016). "Those that effect a change in cell-cell cohesiveness (e.g. VIM, SPARC, COL4A1, and the integrins, ITGA4 and ITGAV), and have been shown to be over expressed in human or mouse melanoma samples, are each associated with one or more UV-miRNAs." (PMID 27149382, 2016). "Self-renewing melanoma progenitor cells expressed nestin and both intermediate filament proteins nestin and vimentin were found to colocalize in melanoma." (PMID 26421614, 2015). "A substantial decrease (2.3 x) was seen in the level of vimentin, a marker of epithelial to mesenchymal transition and the metastatic properties of melanoma." (PMID 24392146, 2014). "In the present study, fisetin reduced the expression of vimentin in melanoma cells and as well as in three-dimensionally reconstituted human melanoma skin equivalents." (PMID 24466036, 2014). "For example, in B16 melanoma cells treated with cyclohexamide a decrease in vimentin mRNa was seen, together with a decrease in the formation of lung metastastes in mice." (PMID 24392146, 2014). "Fisetin treatment significantly reduced mesenchymal marker proteins such as N-cadherin, vimentin, snail and fibronectin in these melanoma cell lines." (PMID 24466036, 2014). "The results of a proteomic 2DE experiment on melanoma cells confirm the multiisofomic pattern of vimentin." (PMID 24392146, 2014). "Four of the proteins with increased levels in highly metastatic melanoma cells were also seen in our study: Vimentin and TIM levels decreased after proton beam treatment, and STRAP and Actinin 4 increased." (PMID 24392146, 2014). "To test the impact of vimentin expression on cell migration and invasion we performed either silencing or over-expression in endothelial and melanoma cells." (PMID 23785295, 2013). "A closer examination of the vimentin phosphorylation pattern showed a preferential Ser459 phosphorylation in the cellular protrusions of melanoma cells." (PMID 24282534, 2013). "To determine the correlation between PARP-1 expression and disease progression in human melanoma, we used IHC to analyze the levels of vimentin, PARP-1, Snail1, E-cadherin and MITF in nodular and metastatic melanoma frozen biopsies." (PMID 23785295, 2013).